ADAMTS13 (ADAM metallopeptidase with thrombospondin type 1 motif 13)
Diseases named in the same sentence as ADAMTS13 in open-access papers (continued):
Sharing a sentence is not in itself a finding about the gene and the disease.
preeclampsia (14 papers, 2016 to 2025). Preeclampsia is a hypertensive disorder of pregnancy that is characterized by new-onset hypertension with proteinuria presenting after 20 weeks of gestation, and depending on mild or severe forms may initially present with severe headache, visual disturbances, and hyperreflexia. "Nevertheless, investigating ADAMTS13 activity in preeclampsia can provide insights into the underlying pathophysiological mechanisms of the disorder." (PMID 38673014, 2024). "In summary, measuring the ADAMTS13 activity in patients diagnosed with preeclampsia is important for accurate diagnosis, prognostication, guiding therapeutic decisions, and advancing our understanding of the pathophysiology of this complex disorder." (PMID 38673014, 2024). "The use of ADAMTS13 activity is important for patients diagnosed with preeclampsia for several reasons." (PMID 38673014, 2024). "The study reveals a statistically significant reduction in ADAMTS13 activity and an elevation in soluble C5b-9 levels among a group of pregnant women who developed early onset severe preeclampsia, compared to a healthy control group." (PMID 38673014, 2024). "This study aimed to examine the involvement of ADAMTS13, von Willebrand, and the complement system in the pathogenesis of preeclampsia/HELLP syndrome." (PMID 38673014, 2024). "The results of our study indicate that a specific group of pregnant women suffering from preeclampsia demonstrated a decline in ADAMTS13 activity, which exhibited a positive correlation with vWFAg levels." (PMID 38673014, 2024). "A portion of pregnant women with preeclampsia showed a decline in ADAMTS13 activity, correlated with vWFAg levels." (PMID 38673014, 2024). "In TTP, there is a typically severe ADAMTS13 deficiency, leading to excessive von Willebrand factor activity and microthrombi formation, while in preeclampsia, ADAMTS13 activity is usually lower but within normal range." (PMID 38673014, 2024). "Recently, one study proposed that the ADAMTS13-von Willebrand factor pathway play a key role in normal pregnancy and pathogenesis of preeclampsia." (PMID 33549121, 2021). "Furthermore, the investigation identified a number of genetic variants in the genes of ADAMTS13, C3, CFH, CFB, thrombomodulin, MBL2, and MASP2 that were significantly linked with the occurrence of preeclampsia, according to the results of analyses A and B." (PMID 38673014, 2024). "Patients with preeclampsia had a decreased ADAMTS13 activity and increased C5b-9 levels." (PMID 38673014, 2024). "There is a question as to whether ADAMTS13 can be used as a reliable biomarker to diagnose preeclampsia/HELLP syndrome." (PMID 38673014, 2024). "Furthermore, it was interesting to find that ADAMTS13 activity was significantly lower in patients with preeclampsia [median (IQR, p25–p75): 70.1% (16.9, 65.3–82.2) vs. 89.5% (25.2, 71.8–97), p = 0.012], but remained within normal limits in both groups." (PMID 38673014, 2024). "Consequently, even if a deficient level of ADAMTS13 activity is highly diagnostic of TTP, a more average one cannot exclude the possibility of HELLP syndrome/preeclampsia." (PMID 35409211, 2022). "Twenty women (7%), diagnosed with preeclampsia or HELLP syndrome, were studied for ADAMTS13 parameters to discard TTP diagnosis." (PMID 35845285, 2021). "In a cohort of 16 women with cTTP and harboring the same mutation of ADAMTS-13, 6 who did not receive prophylactic FFP developed early-onset preeclampsia." (PMID 39995752, 2025). "Nevertheless, it is believed that a complete absence of ADAMTS13 activity is not compatible with the diagnosis of HELLP syndrome/preeclampsia." (PMID 35409211, 2022). "The question is whether ADAMTS13 could be considered a reliable biomarker for the diagnosis of TTP, since there are several studies supporting a statistically significant decrease in ADAMTS13 in other TMAs, such as HELLP syndrome/preeclampsia." (PMID 35409211, 2022).
preeclampsia (continued). "However, the absence of ADAMTS13 activity cannot be equated with a diagnosis of preeclampsia." (PMID 38673014, 2024). "Consequently, besides the strong correlation between significantly low levels of ADAMTS13 activity (below 10–20%) and TTP, a more average level cannot rule out preeclampsia." (PMID 38673014, 2024).
HELLP syndrome (13 papers, 2010 to 2025). A life-threatening condition that can potentially complicate pregnancy. "Third, plasma ADAMTS-13 antigens and activity are reduced in patients with PE or HELLP syndrome, resulting in a kinetic ADAMTS-13 deficiency and hyperadhesive VWF." (PMID 33212799, 2020). "These conditions might be the cause of acquired TTP, HUS, or HELLP syndrome (hemolysis, elevated liver enzymes, low platelets), or the trigger in individuals with a genetic predisposition to ADAMTS-13 or complement factor H deficiency." (PMID 25386342, 2014). "More interestingly, it appears that the key to the differential diagnosis between TTP and HELLP syndrome is ADAMTS13 activity, which is a biomarker widely used in clinical practice." (PMID 35409211, 2022). "Several studies investigated the relationship between the levels of ADAMTS13 activity and the development of PE/HELLP syndrome." (PMID 35409211, 2022). "ADAMTS13’s involvement in the pathophysiology of PE/HELLP syndrome remains elusive." (PMID 38673014, 2024). "ADAMTS13 activity values can vary from 12% to 43% in HELLP syndrome." (PMID 35409211, 2022). "With respect to constitutive TTP, this study supports ADAMTS-13 activity assessment in the setting of HELLP syndrome, even done retrospectively, as this can clarify diagnosis, allowing prevention of maternal morbidity/mortality and leading to successful childbirth." (PMID 26081109, 2015). "Although in pre-eclampsia and HELLP syndrome ADAMTS-13 activity is reduced (median 31%, range 12%–43%), in an acute TTP episode the ADAMTS-13 activity levels are below 10%." (PMID 25386342, 2014). "Differentiating between TTP and HELLP syndrome can be challenging clinically, as the ADAMTS13 assay does not aid in early diagnosis." (PMID 38758904, 2024). "ADAMTS13 is undetectable in TTP, whereas lower levels are found in patients with HELLP syndrome." (PMID 35409211, 2022). "Through laboratory testing, other etiologies such as TTP, Shiga-toxin-producing Escherichia coli HUS (STEC-HUS), and HELLP syndrome were ruled out based on negative ADAMTS13 activity, Shiga toxin testing, and the timing of symptom onset with the associated clinical presentation, respectively." (PMID 40951196, 2025).
liver cirrhosis (13 papers, 2011 to 2025). "ADAMTS-13 was also reduced in patients with decompensated liver cirrhosis and severe alcoholic hepatitis." (PMID 37443746, 2023). "The imbalance in the ADAMTS13 enzyme–VWF substrate (i.e., the decrease in ADAMTS13 activity (ADAMTS13:AC) and increase in VWF antigen (VWF:Ag)) was associated with the severity of liver cirrhosis (LC), acute liver failure (ALF), and severe alcoholic hepatitis." (PMID 36829443, 2023). "In a recent study including 86 patients diagnosed with liver cirrhosis, the lowest levels of ADAMTS-13/VWF and the highest levels of FVIII/PC were found in patients developing decompensation during follow-up." (PMID 37443746, 2023). "ADAMTS13 specifically cleaves the multimeric von Willebrand factor (VWF), and an imbalance between ADAMTS13 activity (ADAMTS13:AC) and VWF antigen (VWF:Ag) levels is associated with the severity of liver cirrhosis (LC)." (PMID 35407443, 2022). "As the etiology of liver cirrhosis was classified into seven different groups with relatively small group sizes, we did not attempt to determine whether there is an association between ADAMTS-13 levels and the etiology of liver cirrhosis - our study was underpowered to answer these questions." (PMID 29849584, 2018). "The presence of decreased ADAMTS-13 levels in a patient with liver cirrhosis can suggest PVT and warrants further evaluation through medical imaging." (PMID 29849584, 2018). "The aim of this study is to evaluate serum ADAMTS-13 levels as a marker of portal vein thrombosis (PVT) in patients with decompensated liver cirrhosis of various origins." (PMID 29849584, 2018). "To determine prognostic factors for patients with liver cirrhosis in the post-ACLF group, we performed multivariate analysis using VWF:Ag/ADAMTS13:AC, CLIF-C ACLF score, Cre, and MELD score, which had p-values <0.1 in the univariate analysis." (PMID 36829443, 2023). "Low serum ADAMTS-13 levels can be a useful indicator of portal thrombosis in patients with decompensated liver cirrhosis irrespective of Child-Pugh or MELD scores." (PMID 29849584, 2018). "We assessed serum ADAMTS-13 levels in patients with decompensated liver cirrhosis, with and without PVT." (PMID 29849584, 2018). "Serum ADAMTS-13 levels, age, platelet count (PLT), and INR (international normalized ratio) were evaluated in (n = 64) patients with liver cirrhosis either with PVT (group 1, n = 31) or without PVT (group 2, n = 33)." (PMID 29849584, 2018).
malaria (13 papers, 2009 to 2023). Malaria is a serious and sometimes fatal disease caused by a parasite that commonly infects a certain type of mosquito which feeds on humans. "In line with previous findings, cytoadherence linked proteins VWF and ADAMTS13 were identified to vary in plasma abundance between malaria-infected and uninfected individuals." (PMID 30442134, 2018). "The present study revealed that rs4962153-A of ADAMTS13 was significantly associated with protection against cerebral malaria in 708 Thai malaria patients." (PMID 22168261, 2011). "In concordance with previous studies ADAMTS13-activity and sP-selectin remained unchanged in early malaria in this study." (PMID 26743539, 2016). "In severe malaria patients, also reduced levels of von Willebrand factor (vWF) cleaving protease, ADAMTS13, and increased vWF levels have been found." (PMID 26743539, 2016). "More recently, the role of ADAMTS13 (a von Willebrand factor (VWF) cleaving protease) activity has also been discussed to explain malaria-related microangiopathy." (PMID 24812562, 2014). "A previous study has shown that not only plasma ADAMTS13 activity but also plasma ADAMTS13 concentration were reduced in cerebral or severe malaria patients compared to healthy controls." (PMID 22168261, 2011). "Together with the presence of abnormal circulating ULVWF multimers, a significant reduction in plasma ADAMTS13 function was also observed in cerebral or severe malaria patients compared to healthy controls." (PMID 22168261, 2011). "This ability of malaria plasma to directly inhibit ADAMTS13 activity was confirmed by spiking malarial plasmas with recombinant human ADAMTS13." (PMID 19300493, 2009). "ADAMTS13 antigen levels were significantly lower in children with severe malaria at presentation than in controls." (PMID 19300493, 2009). "Our eQTL mapping identified ADAMTS13 gene on chr9q34 outside the malaria genomic risk locus which would not have been identified by the conventional SNP mapping approach." (PMID 34868193, 2021). "However, in symptomatic Indonesian malaria patients ADAMTS13-activity was found to be reduced, indicating that a decrease in this enzyme probably occurs at later stages of malaria." (PMID 26743539, 2016). "There is also a recent interest for the determination of ADAMTS13 activity in severe malaria." (PMID 24812562, 2014). "Since platelet-decorated ULVWF strings are cleaved and regulated by ADAMTS13, rs4962153 may influence platelet counts in malaria patients." (PMID 22168261, 2011). "Although ADAMTS13 is a candidate gene for cerebral malaria, no genetic association study of ADAMTS13 in malaria patients has been conducted." (PMID 22168261, 2011). "Together with reduced ADAMTS13 levels, and an unidentified inhibitor of ADAMTS13, this may contribute to the pathophysiology of malaria." (PMID 19300493, 2009). "To investigate whether the reduction in ADAMTS13 activity in malaria plasma might be attributable to the presence of an inhibitor, we performed mixing studies of malaria and normal plasma respectively." (PMID 19300493, 2009). "Nevertheless, whether this modest reduction in plasma ADAMTS13 plays an important role in mediating the ULVWF accumulation in severe malaria remains unclear." (PMID 19300493, 2009). "The reduced activity of ADAMTS13 in malaria patients may allow overproduction of ULVWF multimers." (PMID 22168261, 2011). "Since the frequency of rs4962153-A was higher in mild malaria patients than in cerebral malaria patients, rs4962153-A may enhance the plasma level of ADAMTS13, although platelet counts were not affected by rs4962153-A." (PMID 22168261, 2011). "Since variation screening of the ADAMTS13 gene for Thai malaria patients was not conducted, the possibility that the association between rs4962153 and cerebral malaria detected in the present study has been caused by LD from the other polymorphisms cannot be excluded." (PMID 22168261, 2011).
coronary artery disease (12 papers, 2017 to 2026). "A recent MR study focused on the association between ADAMTS13 activity and ischemic heart disease, suggesting that ADAMTS13’s role may be sex-specific owing to lower ADAMTS13 activity in male than female patients, which is the same as that reported in another study." (PMID 34276770, 2021). "The SNP rs41314453, which is functionally relevant to ADAMTS13 activity, was found to be inversely related to ischemic heart disease (IHD)." (PMID 40724958, 2025). "Low plasma ADAMTS13 activity has been shown to predict cardiac and cerebrovascular events in patients with established coronary artery disease." (PMID 34564132, 2021). "Plasma VWF:Ag levels are increased in coronary artery disease, ischaemic stroke, and venous thromboembolism, whereas ADAMTS13 activity levels are reduced." (PMID 34564132, 2021). "The ADAMTS13 haplotype QAGA or H4 had an independent protective effect on coronary artery disease (CAD)." (PMID 34276770, 2021). "Furthermore, genetic predictors of ADAMTS-13 activity were derived from a GWAS, involving 5448 individuals of European ancestry, in order to evaluate the role of ADAMTS13 in ischemic heart disease." (PMID 40724958, 2025).
systemic lupus erythematosus (12 papers, 2015 to 2025). An autoimmune multi-organ disease typically associated with vasculopathy and autoantibody production. "In patients with lupus, ADAMTS13 IgG antibodies inhibit the proteolytic activity of the metalloproteinase." (PMID 41466911, 2025). "Early ADAMTS13 testing and timely incorporation of caplacizumab may help reduce mortality in autoimmune TTP, including lupus-associated cases." (PMID 41466911, 2025). "A type I IFN gene signature has been described in patients with incomplete lupus, and a pediatric study suggests that severely reduced ADAMTS13 activity in TTP patients might portend the onset of SLE." (PMID 25671313, 2015). "The remainder (over 90%) are ascribed to auto-antibody formation against ADAMTS-13 arising spontaneously or secondary to a number of states including collagen vascular disorders like systemic lupus erythematosus (SLE), pregnancy, post-transplantation or after drug exposure." (PMID 30559606, 2018). "In a previous study of 31 ADAMTS13-deficient TTP patients, 9 had other autoimmune co-morbid conditions, including non-destructive polyarthritis, Raynaud’s phenomenon, autoimmune endocrinopathies, discoid lupus and systemic lupus erythematosus (SLE)." (PMID 25671313, 2015). "ADAMTS13 autoantibodies, TTP episodes following infection or type I interferon treatment and reported ensuing systemic lupus erythematosus in some patients suggest immune dysregulation." (PMID 25671313, 2015). "Workup for autoimmune disorders ruled out systemic lupus erythematosus (SLE), and ADAMTS13 activity was found to be normal, with no ADAMTS13 inhibitor autoantibodies identified." (PMID 39318635, 2024). "Thus it is absolutely important to obtain ADAMTS13 testing in a lupus patient with TMA, and if ADAMTS13 activity is not absent, consider aHUS." (PMID 27766045, 2016). "Systemic lupus erythematosus (SLE)-related TMA includes both acquired TTP, in which ADAMTS13 activity is significantly reduced, and secondary TMA, in which ADAMTS13 activity is not reduced." (PMID 35979405, 2022).
acquired thrombotic thrombocytopenic purpura (11 papers, 2018 to 2026). Acquired thrombotic thrombocytopenic purpura is the non-hereditary form of thrombotic thrombocytopenic purpura (TTP), characterized by profound peripheral thrombocytopenia, microangiopathic hemolytic anemia (MAHA) and single or multiple organ failure of variable severity. "Autoimmune thrombotic thrombocytopenic purpura (iTTP) is a life-threatening, relapsing disease in which an acquired deficiency of the enzyme ADAMTS13 leads to generalised microvascular thrombosis." (PMID 33477992, 2021). "Autoimmune thrombotic thrombocytopenic purpura (iTTP) is a potentially life-threatening, relapsing disease in which an acquired deficiency of the von Willebrand factor (VWF)-cleaving protease, ADAMTS13, leads to generalised microvascular thrombosis in various organs." (PMID 33477992, 2021). "Monitoring ADAMTS13 activity is essential to distinguish congenital from acquired thrombotic thrombocytopenic purpura, guide treatment decisions, and prevent relapses." (PMID 41852235, 2026). "In clinical immunology and for research purposes, AAPCs represent a convenient platform to monitor CD4+ T cell responses in patients against allergens, autoantigens, or infectious antigens, as it was shown with the antigen ADAMTS13 involved in acquired thrombotic thrombocytopenic purpura." (PMID 31156634, 2019). "ADAMTS-13 activity is normal in pseudo-TMA, while in hereditary or acquired TTP it should be <10%." (PMID 36128212, 2022).
atrial fibrillation (11 papers, 2020 to 2025). A disorder characterized by an electrocardiographic finding of a supraventricular arrhythmia characterized by the replacement of consistent P waves by rapid oscillations or fibrillatory waves that vary in size, shape and timing and are accompanied by an irregular ventricular response. "Alterations in both VWF and ADAMTS13 levels have also been implicated in patients with atrial fibrillation (AF)." (PMID 34564132, 2021). "Low ADAMTS-13 and high VWF have been associated with cardiovascular disease and atrial fibrillation (AF)." (PMID 37255854, 2023). "Dialysis patients have highly increased risks of atrial fibrillation and VWF and ADAMTS13 have been associated with worse outcomes in patients with atrial fibrillation." (PMID 34134634, 2021). "•Low ADAMTS-13 predicted death, and low VWF was associated with new-onset atrial fibrillation." (PMID 37255854, 2023). "Therefore, atrial fibrillation could play an important role in the association between VWF and ADAMTS13 and mortality in dialysis patients." (PMID 34134634, 2021). "Finally, we could not investigate the association between VWF and ADAMTS13 and mortality in a subgroup of patients with atrial fibrillation, since we had no information about the presence of atrial fibrillation in our cohort." (PMID 34134634, 2021).
cerebral infarction (11 papers, 2013 to 2025). An ischemic condition of the brain, producing a persistent focal neurological deficit in the area of distribution of the cerebral arteries. "Deficiency of ADAMTS13 is associated with the occurrence of microthrombosis followed by ischemic complications, such as cerebral infarction." (PMID 37446186, 2023).